CYB5R2 (cytochrome b5 reductase 2)
Description:
NADH-cytochrome b5 reductases are involved in desaturation and elongation of fatty acids, cholesterol biosynthesis, drug metabolism, and, in erythrocyte, methemoglobin reduction (By similarity). Responsible for NADH-dependent lucigenin chemiluminescence in spermatozoa by reducing both lucigenin and 2-[4-iodophenyl]-3-[4-nitrophenyl]-5-[2,4-disulfophenyl]-2H tetrazolium monosodium salt (WST-1).
Synonyms: b5R.2
Tractability: PROTAC: its protein half-life has been measured.
Gene: Protein-coding gene on chromosome 11 (7,665,097 to 7,677,222, reverse strand). Ensembl gene ENSG00000166394.
Subcellular location (Human Protein Atlas): Golgi apparatus; Nucleoplasm
Pathways (Reactome):
Transport of small molecules: Erythrocytes take up carbon dioxide and release oxygen
Gene Ontology:
Molecular function: cytochrome-b5 reductase activity, acting on NAD(P)H; protein binding; FAD binding; cytochrome-b5 reductase activity, acting on NADH; oxidoreductase activity
Biological process: bicarbonate transport
Cellular component: Golgi apparatus; membrane; nucleus; endoplasmic reticulum membrane; mitochondrion
Genetic constraint (gnomAD): Loss-of-function variants: 37 observed, 33.1 expected, observed/expected ratio (o/e) 1.12, 90% interval 0.86 to 1.47. The upper end of that interval is the gene's LOEUF score, 1.47, which puts it in group 6 of 6, group 1 being the genes least tolerant of losing a copy. Missense variants: 419 observed, 357.47 expected, observed/expected ratio (o/e) 1.17, 90% interval 1.08 to 1.27. Synonymous variants: 169 observed, 136.57 expected, observed/expected ratio (o/e) 1.24, 90% interval 1.09 to 1.41.
Homologues: Orthologues: chimpanzee CYB5R2 (98% identical), macaque CYB5R2 (96% identical), rabbit CYB5R2 (87% identical), mouse Cyb5r2 (82% identical), guinea pig CYB5R2 (82% identical), tropical clawed frog cyb5r2 (66% identical), zebrafish cyb5r2 (62% identical), Caenorhabditis elegans hpo-19 (58% identical), rat Cyb5r2 (57% identical), Drosophila melanogaster CG5946 (55% identical), Caenorhabditis elegans T05H4.4 (54% identical). Paralogues in human: CYB5R3 (59% identical), CYB5R1 (57% identical), CYB5R4 (29% identical), CYB5RL (27% identical), OXNAD1 (18% identical).
Diseases named in the same sentence as CYB5R2 in open-access papers:
CYB5R2 is named in the same sentence as 18 diseases in open-access papers, as found by Europe PMC text mining. Sharing a sentence is not in itself a finding about the gene and the disease. The quoted sentences say what the papers report.
nasopharyngeal carcinoma (5 papers, 2014 to 2022). A carcinoma arising from the nasopharyngeal epithelium. "CYB5R2 is a cytochrome b5 reductase 2, methylation of which in nasopharyngeal carcinoma was associated with lymph node metastasis." (PMID 33473258, 2020). "CYB5R2 was shown to upregulate genes that negatively impact angiogenesis in nasopharyngeal cancer cells and downregulate expression of vascular endothelial growth factor, thereby suppressing angiogenesis and tumor migration." (PMID 36441026, 2022). "Akin to the nasopharyngeal cancer study, CYB5R2 was found to be hypermethylated in prostate cancer in a tissue-specific manner, thereby facilitating prostate pathogenesis." (PMID 36441026, 2022). "It was recently shown that CYB5R2 may act as a tumor suppressor gene in human nasopharyngeal cancer." (PMID 36441026, 2022). "CYB5R2 is considered to be a tumor suppressor in prostate cancer and nasopharyngeal cancer." (PMID 36081566, 2022). "Cytochrome b5 reductase 2 (CYB5R2) is a potential tumor suppressor that inhibits cell proliferation and motility in nasopharyngeal carcinoma (NPC)." (PMID 26275421, 2015).
lymph node metastasis (4 papers, 2014 to 2022). "In previous study, we showed that promoter DNA hypermethylation was responsible for inactivation of CYB5R2 and associated with lymph node metastasis in NPC patients." (PMID 26275421, 2015). "Five genes (VEGFA, IFNB1, IGF1, TEK, and TGFBR1) are associated with angiogenesis, which provides clues to the mechanism of the association between epigenetic inactivation of CYB5R2 and lymph node metastasis." (PMID 26275421, 2015). "Clinically, CYB5R2 methylation was associated with lymph node metastasis in NPC patients (P < 0.05)." (PMID 24338690, 2014). "Inactivation of CYB5R2 is associated with lymph node metastasis in NPC." (PMID 26275421, 2015). "CYB5R2 promoter methylation associated with lymph node metastasis, suggesting that downregulation of CYB5R2 protein expression and methylation of its promoter in nasopharyngeal epithelium could potentially be used to forecast lymph node metastasis." (PMID 36441026, 2022). "Our finding that CYB5R2 promoter methylation is associated with lymph node metastasis in NPC, suggests that CYB5R2 promoter methylation may serve as a diagnostic indicator of lymph node metastasis, which would have great value for the clinical evaluation of NPC cases." (PMID 24338690, 2014).
prostate carcinoma (3 papers, 2018 to 2022). A carcinoma that arises from epithelial cells of the prostate gland. "These new findings demonstrate a potential role of CYB5R2 in mitigating the progression of prostate cancer, which could lead to the development of therapeutics that effectively target the expression or stability of CYB5R2." (PMID 36441026, 2022). "This implies that CYB5R2 may protect against prostate cancer." (PMID 36441026, 2022).
colorectal cancer (1 paper, 2022). A primary or metastatic malignant neoplasm that affects the colon or rectum. "However, further studies are needed to further illuminate the clinical implications of CYB5R2 frameshift mutations in colorectal cancer." (PMID 36441026, 2022). "These novel findings present a unique role of CYB5R2 in the pathogenesis of colorectal cancer and could lead to potential therapeutic interventions." (PMID 36441026, 2022).
invasive breast carcinoma (1 paper, 2014). A carcinoma that infiltrates the breast parenchyma. "Consistent with our findings, microarray analysis revealed that CYB5R2 is downregulated in lobular and ductal invasive breast cancer biopsies and functions as a regulator of cell proliferation, differentiation and transformation." (PMID 24338690, 2014).
lung carcinoma (1 paper, 2024). "Neither CYB5R1 nor CYB5R2 was detected in human lung cancer cells." (PMID 38253797, 2024).
prostate tumours (1 paper, 2015). "Several other genes at this locus, including CYB5R2, EIF3F, NLRP10, OLFML1 and OVCH2, were also found to be significantly expressed in prostate tumours in comparison with normal tissues." (PMID 26443449, 2015).
psoriasis (1 paper, 2012). An autoimmune condition characterized by red, well-delineated plaques with silvery scales that are usually on the extensor surfaces and scalp. "For example, PTPN22 is a psoriasis risk gene with polymorphisms associated with early onset psoriasis, and CYB5R2 is involved in fatty acid metabolism." (PMID 22957057, 2012).
tumor (7 papers, 2007 to 2022). "Thus, ectopic expression of CYB5R2 reverses the tumor growth which is associated with its epigenetic downregulation in the HONE1 cells." (PMID 24338690, 2014). "CYB5R2 was related to many proteases and toll-like receptor family, indicating a possible role in tumor invasion and immunoregulation." (PMID 35621670, 2022). "The results of this study provide insight into the mechanism by which CYB5R2 acts to suppress tumor function, and further support CYB5R2 as a novel TSG in NPC." (PMID 26275421, 2015). "As well, CYB5R2 expression was downregulated in the 20 NPC primary tumor biopsies but easily detected in all NNE samples." (PMID 24338690, 2014). "We report here the first instance of epigenetic downregulation in NPC tumor biopsies of a key enzyme, CYB5R2, which is responsible for the detoxification of environmental carcinogens." (PMID 24338690, 2014). "Genes encoding proteins involved in ion and electron transport (CYB5R2, GABRP), and genes encoding proteins with transcription factor and regulator activity (ELF5, ID4) were downregulated in both populations of tumor cells." (PMID 17389037, 2007). "In addition, exogenous expression of CYB5R2 significantly inhibited the proliferation, colony formation, migration, and in vivo tumor formation of NPC cells, which suggests that CYB5R2 is a potential TSG of NPC." (PMID 26275421, 2015). "We further assessed the tumor suppressing capacity of CYB5R2 in vivo." (PMID 24338690, 2014). "In addition, epigenetic silencing of CYB5R2 was a tumor-specific event and could be detected in both early- and advanced-stage NPC biopsies, which suggests that CYB5R2 promoter hypermethylation might contribute both to the initiation and progression of NPC." (PMID 24338690, 2014). "In this study, we evaluated the transcriptional levels and methylation status of CYB5R2 in NPC cell lines and primary tumor biopsies." (PMID 24338690, 2014). "Two of these, GSTP1 and SPINT2 were previously reported tumor suppressor genes which were hypermethylated in tumors with corresponding down-regulated gene expression, while the other 2 (CYB5R2 and SH3YL1) represent potential novel tumor suppressor genes." (PMID 25093504, 2014). "Here, we investigate the transcript levels and promoter methylation status of CYB5R2 in NPC derived cell lines and tumor biopsies and experimentally address its role as a tumor suppressor gene." (PMID 24338690, 2014). "CYB5R2 overexpression in NPC cells up-regulated the expression of genes that negatively modulate angiogenesis and down-regulated the expression of the pro-angiogenic factor VEGF, resulting in reduced angiogenesis and, thereby, a suppression of tumor formation." (PMID 26275421, 2015). "To determine the mechanisms involved in the tumor suppressive effect of CYB5R2 on NPC cells, we first confirmed that CYB5R2 mRNA level was increased in NPC cells (CNE2 and HONE1) after transfection with a CYB5R2 expression plasmid." (PMID 26275421, 2015). "CYB5R2 up-regulates the expression of genes that negatively modulate angiogenesis in NPC cells and down-regulates the expression of VEGF to reduce angiogenesis, thereby suppressing tumor formation." (PMID 26275421, 2015). "We find that CYB5R2 transcript levels are decreased in NPC cell lines and tumor biopsies." (PMID 24338690, 2014). "CYB5R2 may therefore suppress tumor angiogenesis, but the detailed molecular mechanism has not yet been fully explained." (PMID 26275421, 2015). "We found, using PCR assays, that the overexpression of CYB5R2, a potential TSG, affected the transcription of genes involved in several major cancer-related pathways, including apoptosis, cell cycle, cell adhesion, angiogenesis, and tumor invasion and metastasis." (PMID 26275421, 2015).
cancer (4 papers, 2014 to 2025). A tumor composed of atypical neoplastic, often pleomorphic cells that invade other tissues. "Four of the genes (RARβ2, SPARC, CDH13, CYB5R2) showed significantly higher methylation in the cancer cases when compared with the control cases (p<0.05)." (PMID 30204798, 2018). "In summary, our data demonstrate for the first time that CYB5R2 is epigenetically inactivated by promoter hypermethylation in a human cancer, NPC." (PMID 24338690, 2014). "The expression of CYB5R2 varies in different types of cancer." (PMID 26275421, 2015). "Four genes (CDH13, CYB5R2, RARB2 and SPARC) showed the expected significant hypermethylation (p < 0.05) in cancer patients compared with HDs, whereas DRD2 and LINE-1 were hypomethylated (p < 0.05), as anticipated." (PMID 41008642, 2025). "We observed close correlation between aging and DNA methylation of RARβ2, CYB5R2 and TIMP3 suggesting that the prevalence of these methylation signals in these cancer-related genes could heighten the development of PCa in older AA men." (PMID 30204798, 2018).
adenocarcinoma (1 paper, 2024). A common cancer characterized by the presence of malignant glandular cells. "In moderate and poor adenocarcinomas, the expression of the CYB5R3 gene, but not CYB5R1 and CYB5R2/4, was decreased." (PMID 38791014, 2024).
prostate (1 paper, 2022). "This study illustrates that epigenetic dysregulation of critical regulatory components, such as CYB5R2, can favor prostate carcinogenesis." (PMID 36441026, 2022).
CYB5R2 also shares sentences with these, for which no sentence is quoted: breast carcinoma (1 paper); diabetic retinopathy (1); hypopharyngeal cancer (1); infection (1); lung adenocarcinoma (1); varicocele (1).